CISH (cytokine inducible SH2 containing protein)
Description:
SOCS family proteins form part of a classical negative feedback system that regulates cytokine signal transduction. CIS is involved in the negative regulation of cytokines that signal through the JAK-STAT5 pathway such as erythropoietin, prolactin and interleukin 3 (IL3) receptor. Inhibits STAT5 trans-activation by suppressing its tyrosine phosphorylation. May be a substrate-recognition component of a SCF-like ECS (Elongin BC-CUL2/5-SOCS-box protein) E3 ubiquitin-protein ligase complex which mediates the ubiquitination and subsequent proteasomal degradation of target proteins (By similarity).
Synonyms: CIS; SOCS; G18; CIS-1; BACTS2
Tractability: Antibody: its Gene Ontology location is reachable by antibodies, with medium confidence. PROTAC: UniProt records ubiquitination sites on it.
Gene: Protein-coding gene on chromosome 3 (50,606,456 to 50,611,774, reverse strand). Ensembl gene ENSG00000114737.
Subcellular location (Human Protein Atlas): Microtubules; Cytokinetic bridge
Pathways (Reactome):
Immune System: Growth hormone receptor signaling; Interleukin-7 signaling
Metabolism of proteins: Neddylation
Gene Ontology:
Molecular function: protein binding; cytokine receptor binding
Biological process: cytokine-mediated signaling pathway; intracellular signal transduction; negative regulation of receptor signaling pathway via JAK-STAT; regulation of cell growth; protein ubiquitination
Cellular component: cytosol; plasma membrane
Genetic constraint (gnomAD): Loss-of-function variants: 11 observed, 19.04 expected, observed/expected ratio (o/e) 0.58, 90% interval 0.36 to 0.96. The upper end of that interval is the gene's LOEUF score, 0.96, which puts it in group 4 of 6, group 1 being the genes least tolerant of losing a copy. Missense variants: 280 observed, 359.94 expected, observed/expected ratio (o/e) 0.78, 90% interval 0.7 to 0.86. Synonymous variants: 118 observed, 145.17 expected, observed/expected ratio (o/e) 0.81, 90% interval 0.7 to 0.95.
Homologues: Orthologues: chimpanzee CISH (98% identical), macaque CISH (97% identical), pig CISH (92% identical), rabbit CISH (91% identical), dog CISH (91% identical), mouse Cish (91% identical), rat Cish (91% identical), guinea pig CISH (88% identical), tropical clawed frog cish (56% identical), zebrafish cisha (39% identical), zebrafish cishb (33% identical), Drosophila melanogaster Socs44A (21% identical), and 1 more. Paralogues in human: SOCS2 (32% identical), SOCS7 (28% identical), SOCS6 (28% identical), SOCS3 (26% identical), SOCS5 (24% identical), SOCS1 (23% identical), SOCS4 (23% identical).
Diseases named in the same sentence as CISH in open-access papers:
CISH is named in the same sentence as 175 diseases in open-access papers, as found by Europe PMC text mining. Sharing a sentence is not in itself a finding about the gene and the disease. The quoted sentences say what the papers report.
viral infection (22 papers, 2008 to 2026). "The CISH locus has been associated with major infectious diseases such as bacteraemia, tuberculosis, malaria, and viral infections such as hepatitis B, suggesting shared susceptibility genes among different infections." (PMID 28727728, 2017).
breast carcinoma (20 papers, 2003 to 2025). "This increases Stat5a-mediated transcription and elevates the protein expression of breast cancer proliferative genes, such as CISH, CEBPb (CCAAT/enhancer binding protein β), and cyclin D1, which promote the proliferation of breast cancer." (PMID 40092489, 2025). "In vivo CISH absence favors NK cell numbers to the tumor burden, optimizes their killing properties and limits NK cell exhaustion leading to primary breast cancer growth in addition to superior control of spontaneous tumor metastasis." (PMID 35884417, 2022). "In breast cancer, only one study analyzed CISH expression in only 17 cases." (PMID 35884417, 2022). "Cytokine-inducible SH2-containing protein (CIS) was found to interact with JAK1, induce proteasomal degradation in NK cells and then mediate resistance to melanoma and prostate and breast cancer metastasis." (PMID 36104718, 2022). "We found heterogeneous expression of CISH in TNBC samples, as reported at the protein and mRNA levels in the unique and small series of 17 breast cancers and 3 normal breast tissues." (PMID 35884417, 2022). "Except the small above-quoted series, no data about CISH expression in breast cancer are available in the literature." (PMID 35884417, 2022). "To date, no data are available regarding the prognostic value of CISH in breast cancer, whereas the expression of certain SOCS genes has already been associated with better prognosis." (PMID 35884417, 2022). "Cloning of the promoter region of the CISH gene into the improved pGL4.10 luciferase reporter construct resulted in a highly sensitive, PRL-responsive reporter that should be of widespread utility in examining PRL/Stat5 pathway in ER+ human breast cancer cells." (PMID 18254957, 2008).
Obesity (19 papers, 2010 to 2025). Accumulation of substantial excess body fat. "Other novel methylation markers, cg27589809 (CISH), and cg20560869 (NR4A1), are associated with obesity." (PMID 32709145, 2020). "For SOCS3, CISH, PIM3 (Pim-3 proto-oncogene, serine/threonine kinase), and KLF4 (Kruppel-like factor 4), obesity was associated with decreased methylation and increased gene expression, while for HRASLS2, obesity was associated with decreased methylation and decreased gene expression." (PMID 29312471, 2018).
hepatocellular carcinoma (15 papers, 2007 to 2024). A malignant tumor that arises from hepatocytes. "The ectopic expression of SOCS2 and CISH in liver-related cell line leghorn strain M chicken hepatoma (LMH) cell and immortalized chicken preadipocytes (ICP) revealed that these two genes can regulate fatty acid metabolism, adipocyte differentiation, and lipid droplet accumulation." (PMID 33519913, 2020).
tuberculosis (14 papers, 2012 to 2024). A chronic, recurrent infection caused by the bacterium Mycobacterium tuberculosis. "An association has been shown between CISH polymorphisms and susceptibility to infectious diseases including malaria, bacteremia or tuberculosis." (PMID 34072601, 2021). "Tuberculosis-associated single nucleotide polymorphisms (SNPs) (i.e., rs809451, rs414171, rs2239751) are located in CISH promoter regions and were accompanied with differential CIS expression." (PMID 29411179, 2018). "Recent studies have suggested that CISH is involved in human diseases, and polymorphisms in CISH gene are associated with susceptibility to infectious diseases, including bacteremia, malaria, tuberculosis and Hepatitis B." (PMID 24964072, 2014). "In 2010, Khor and colleagues found a relation between CISH variants and susceptibility to bacteremia, malaria and tuberculosis, with rs414171 accounting for most of the association signal." (PMID 25255143, 2014). "In addition, rs414171-T allele that was associated with susceptibility to bacteremia, tuberculosis and malaria has been shown to reduce the promoter activity of CISH and its expression in human PBMCs after stimulation by IL-2." (PMID 34072601, 2021). "Furthermore, genetic CISH variants were found to be associated with susceptibility to infectious diseases including tuberculosis." (PMID 29411179, 2018). "Furthermore, variants of CISH have been associated with susceptibility to infectious disease, including tuberculosis and malaria, in several African populations." (PMID 26616214, 2015). "In conclusion, CISH promoter rs414171 and rs809451 polymorphisms may play a vital role in mediating individual susceptibility to tuberculosis." (PMID 24632804, 2014). "A recent study demonstrated that genetic variation at CISH is associated with susceptibility to bacteremia, malaria, and tuberculosis in several global groups including a Gambian population, indicating the important role that CISH plays in infectious disease susceptibility." (PMID 22570615, 2012). "Accordingly, we propose a hypothesis that CISH promoter polymorphisms may affect expression of the gene thus contributing to a substantial degree of inter-individual variability in the susceptibility to infectious diseases, including tuberculosis." (PMID 24632804, 2014). "Relationship between CISH promoter polymorphism and pediatric tuberculosis (TB), stratified by location and severity of the disease." (PMID 24632804, 2014). "Interestingly, it is located near the CISH gene, and is in strong linkage disequilibrium with four SNPs highly associated with late mortality in patients with septic shock; these includes rs2239751, which has been also associated with tuberculosis, and persistent hepatitis B virus infection." (PMID 34072601, 2021). "Furthermore, human CISH seems to be critical for T-cell proliferation and survival during the response to infection (e.g., tuberculosis and severe malaria)." (PMID 36213116, 2022). "CISH promoter haplotypes distribution in tuberculosis patients and healthy control subjects." (PMID 24632804, 2014).
diabetes (11 papers, 2016 to 2025). "In a cohort of 260 T1D patients from the pediatric diabetes biobank (German Center for Diabetes Research, DZD), three CISH promoter SNPs (i.e., rs809451, rs414171, rs2239751) were analyzed." (PMID 29411179, 2018).
asthma (8 papers, 2011 to 2022). "Recently, in correspondence with our prediction, a review of the inflammation profiling of asthma involving airway smooth muscles identified CISH as a potential methylation biomarker for airway regional inflammation." (PMID 33519902, 2020). "Furthermore, CISH has been reported to exhibit different methylation patterns in different asthma statuses with different interleukin profiles, validating the specific role of CISH in inflammatory lung diseases on the methylation level." (PMID 33519902, 2020).
leukemia (7 papers, 2017 to 2021). A malignant (clonal) hematologic disorder, involving hematopoietic stem cells and characterized by the presence of primitive or atypical myeloid or lymphoid cells in the bone marrow and the blood. "Furthermore, the deletion of cytokine-inducible SH2-containing protein (CISH) in iPSC differentiated NK cells improved persistence and enhanced antitumor activity in a leukemia xenograft model." (PMID 34025641, 2021). "Moreover, we have shed light on the role of microRNAs and suppressors of cytokine signalling (SOCS/CISH) in increasing anti-tumour immunity towards leukaemia." (PMID 34207299, 2021). "Similarly, genetic deletion of a negative regulator of IL-15 signaling, called cytokine-inducible SH2-containing protein or CIS, in iPSC-NK cells led to improved anti-tumor function, both in vitro and in vivo in a leukemia xenograft model." (PMID 33120910, 2020). "In addition to epigenetic modifiers (RMDs) and microRNAs; the role of cytokine-inducible SH2-domain-containing protein (CISH or CIS) as anti-tumour and anti-leukaemia activity, also, cannot be denied because of its versatile role in regulating cytokine signalling via sensitizing immune cells." (PMID 34207299, 2021).
melanoma (7 papers, 2007 to 2022). A malignant, usually aggressive tumor composed of atypical, neoplastic melanocytes. "CISH downregulates interleukin 15 (IL-15) signaling in natural killer cells, and Cish-/- mice injected with murine melanoma cells exhibit greatly reduced metastasis." (PMID 34067095, 2021).
Sepsis (6 papers, 2007 to 2025). Sepsis is defined as life-threatening organ dysfunction caused by a dysregulated host response to infection. "It is not excluded, nevertheless, that other SNPs within the same enhancer or other regulatory regions alter CISH gene expression and susceptibility to sepsis." (PMID 34072601, 2021). "They suggest that genetic variations in key genes, such as CISH, perturb relevant pathways, increasing the risk of death in sepsis patients." (PMID 34072601, 2021). "Interestingly, SNPs associated with late mortality due to sepsis overlap the enhancer marks H3K4me1 and H3K27Ac in K562 cells and monocytes in the CISH-MAPKAPK3 locus." (PMID 34072601, 2021). "Since NK cells in septic patients have been shown to produce low levels of IFNγ and to have a decreased cytotoxicity activity, low levels of CISH may influence susceptibility to sepsis through an NK cell dependent mechanism." (PMID 34072601, 2021). "Further studies depicting the effect of the transcription level of CISH on the intensity of the immune response in monocytes/macrophages, crucial during sepsis development are needed." (PMID 34072601, 2021).
allergic disease (5 papers, 2010 to 2026). An immune response that occurs following re-exposure to an innocuous antigen, and that requires the presence of existing antibodies against that antigen. "CISH has also been identified in the etiology of several human diseases, particularly immune disorders, such as allergy and susceptibility to infectious disease, as well as a potential target to augment immunotherapy." (PMID 41878422, 2026).
colon carcinoma (5 papers, 2014 to 2024). "Thirdly, there is little research on the role of CD22, CASP1, and CISH in colon cancer, even though it plays an important role." (PMID 34026619, 2021). "The risk scores calculated based on the expression levels and coefficients of four mRNAs (ALCAM, CD22, CASP1, and CISH) might be used to precisely and independently predict the prognosis of colon cancer." (PMID 34026619, 2021). "Recently, a study using an oxaliplatin resistance-related gene signature (consisting of CD22, CASP1, CISH, and ALCAM) to predict the survival of patients with colon cancer found that this gene signature has a better predictive value." (PMID 36145360, 2022). "Afterward, we established a model to predict the prognosis of colon cancer using four oxaliplatin resistance-related genes (ALCAM, CD22, CASP1, and CISH) on the basis of stepwise regression and LASSO Cox regression." (PMID 34026619, 2021). "Thereafter, we established a prognosis signature based on four genes [CD22, CASP1, CISH, and activated leukocyte cell adhesion molecule (ALCAM)] to evaluate the prognosis for colon cancer patients." (PMID 34026619, 2021).
colorectal cancer (5 papers, 2014 to 2025). A primary or metastatic malignant neoplasm that affects the colon or rectum. "In pre-clinical studies, inhibition of other immune checkpoints TGFβ and CIS (an NK cell IL-15 signalling checkpoint encoded by CISH) simultaneously results in enhanced NK cell activation and decreased MC38 colorectal cancer tumor burden in mice." (PMID 38090565, 2023). "Transcriptomic profiling of oxaliplatin-resistant colorectal cancer (CRC) cells derived from DLD1 and HCT116 identified ALCAM activation with concurrent CD22, CASP1, and CISH suppression as key molecular features of oxaliplatin non-response." (PMID 41009436, 2025).
COVID-19 (5 papers, 2020 to 2023). A disease caused by infection with severe acute respiratory syndrome coronavirus 2. "Previous reports have associated differential expression of several constituent genes of the IL2-AIS, including CISH, AREG, DUSP2, NFKBIA and TNFAIP3, in COVID-19 patients." (PMID 37700317, 2023). "For example, in contrast to the transcriptional changes induced by low-dose IL-2 in T1D patients, we observed a downregulation of CISH and an upregulation of AREG in COVID-19 patients during acute infection, across multiple immune cell types." (PMID 37700317, 2023).
influenza infection (5 papers, 2014 to 2024). "To examine further the role of CISH in modulating ILC2 activity in diverse inflammatory settings, we challenged WT or Cish-deficient mice using a model of severe influenza pneumonia." (PMID 34290377, 2021).
allergic asthma (4 papers, 2011 to 2023). A asthma with a basis in a pathological type I hypersensitivity reaction. "CISH knockout mice showed increased susceptibility to experimental allergic asthma and EAE, while SOCS5 was preferentially expressed in the retina and significantly upregulated during the development and resolution EAU." (PMID 36969252, 2023).
glioblastoma (4 papers, 2015 to 2025). The most malignant astrocytic tumor (WHO grade IV). "Thus, the new YT–Vav1+CISH–/– and YT–Vav1+B2M–/– modified NK cell lines demonstrate greater cytotoxic activity against primary patient’s glioblastoma spheroids compared with the standard line, causing early metabolic rearrangements and evident decrease of tumor cells viability." (PMID 40071076, 2025). "In this research, antitumor activity of YT-Vav1+CISH–/– and YT–Vav1+B2M–/– modified NK cell lines was evaluated using a model of 3D tumor spheroids of a patient’s glioblastoma." (PMID 40071076, 2025). "Experiments showed that NK cells with CISH knockout had a more effective impact on the monolayer of human primary glioblastoma culture." (PMID 40071076, 2025). "The study used a primary culture of GBM7-Luc2-mKate2 human glioblastoma, a line of YT (YTwt) wildtype human NK cells, as well as lines created by us with overexpression of VAV1 protein with either CISH (YT–Vav1+CISH–/–) or B2M (YT–Vav1+B2M–/–) knockouts." (PMID 40071076, 2025). "Interestingly, this deletion of CISH, which encodes the protein CIS—a known negative regulator of NK cell activity—aimed to enhance the anti-tumor efficacy of NK cells against glioblastoma (GBM), a highly aggressive brain tumor." (PMID 40299429, 2025).
parasitic infections (4 papers, 2011 to 2023). "Studies exploring viral and parasitic infections in Cish−/− mice are currently underway that aim to directly address the impacts of CISH on the pathogenesis of these agents." (PMID 37628937, 2023).
liver cancer (3 papers, 2021 to 2024). An epithelial or non-epithelial malignant neoplasm that arises from the liver. "SOCS1 alterations through SOCS7 and CISH alterations were detected in liver cancer tissues at the following frequencies: SOCS1, 1.1%; SOCS2, 0.8%; SOCS3, 6%; SOCS4, 0.3%; SOCS5, 1.3%; SOCS6, 1.3%; SOCS7, 2.4%; and CISH, 2.7%." (PMID 39307915, 2024).
lymphoma (3 papers, 2018 to 2025). A malignant (clonal) proliferation of B- lymphocytes or T- lymphocytes which involves the lymph nodes, bone marrow and/or extranodal sites. "In lymphoma models, CD19 UCB-derived CAR NK cells engineered to secrete IL-15 and lacking CISH have shown improved metabolic fitness and antitumor activity." (PMID 40510336, 2025).
acute myelogenous leukemia (2 papers, 2021 to 2022). "The loss of CISH contributes to hyperproliferative responses in acute myelogenous leukemia." (PMID 35453806, 2022).
glioma (2 papers, 2020 to 2025). A benign or malignant brain and spinal cord tumor that arises from glial cells (astrocytes, oligodendrocytes, ependymal cells). "Immune-related pathways such as TNF signalling (IDH3B/G, MDH1, ACO2, SDHA, OGDHL) and JAK/STAT3 (PIAS2/3, PTPN2, AKT1/2, MCL1, CISH, AOX1) signalling are enriched in gliomas and play a critical role in their progression." (PMID 41007296, 2025).
ovarian carcinoma (2 papers, 2020 to 2023). A malignant neoplasm originating from the surface ovarian epithelium. "This study reports for the first time that ovarian cancer (OVCA) development and progression is associated with the enhanced expression of CISH, a marker of NK cell exhaustion, and an increased influx of CISH-expressing cells into the tumor." (PMID 36830840, 2023).
ovarian tumor (2 papers, 2022 to 2023). "The goal of this study was to examine whether the population of CISH-expressing NK cells increased in ovarian tumors during OVCA development and progression and whether CISH-expression was associated with GRP78 and IL-10 levels." (PMID 36830840, 2023). "However, the expression of CISH as a mechanism of suppression of NK cell immunity against ovarian tumors is not known." (PMID 36830840, 2023).